ENSG00000272822 (novel protein)
Gene: Protein-coding gene on chromosome 12 (48,903,503 to 48,957,365, reverse strand). Ensembl gene ENSG00000272822.
Genetic constraint (gnomAD): Loss-of-function variants: 2 observed, 13.16 expected, observed/expected ratio (o/e) 0.15, 90% interval 0.061 to 0.48. Missense variants: 46 observed, 154.93 expected, observed/expected ratio (o/e) 0.3, 90% interval 0.23 to 0.38. Synonymous variants: 47 observed, 58.86 expected, observed/expected ratio (o/e) 0.8, 90% interval 0.63 to 1.02.